INS (insulin)
Diseases named in the same sentence as INS in open-access papers (continued):
Sharing a sentence is not in itself a finding about the gene and the disease.
Insulin resistance (continued). "What can be the link between ceramide and SREBP-1c activation, considering that the strong insulin resistance observed in the fatty liver should impair the effect of insulin, the usual inducer of SREBP-1c expression and cleavage?" (PMID 33669443, 2021). "Due to their etiological similarities, T2D and obesity-induced conditions, including hyperinsulinemia, insulin resistance, hyperglycemia, altered insulin signaling, and inflammation, and their relationship with Aβ metabolism will be discussed concurrently." (PMID 34497507, 2021). "Insulin resistance involves complex and variable disturbances in the insulin signaling pathway, eventually culminating in impaired glucose utilization by muscle and adipose tissues, contributing to the impairment of glycemic control." (PMID 35011666, 2021). "NPY not only modulates insulin secretion, but substantially induces insulin resistance in hepatocytes and adipocytes through Y1R and Y5R." (PMID 33708805, 2021). "HFD feeding increases body weight, leptin and insulin levels as well as insulin resistance in rodents." (PMID 33578998, 2021). "It is suggested that it is caused by placental production of hormones such as leptin, progesterone, cortisol, estrogen, placental growth hormone and lactogen, which increase insulin resistance, whereby women’s insulin secretion is insufficient." (PMID 34836042, 2021). "More and more evidence demonstrates that they impair insulin signaling to induce insulin resistance in high fructose-induced MetS." (PMID 34326769, 2021). "The intracellular accumulation of these by-products impair insulin signalling pathways and contribute to insulin resistance." (PMID 33858477, 2021). "A significant moderate correlation between HOMA-IR and percentage of bleeding upon probing sites and weak correlation between fasting insulin level and BOP% confirm the association between insulin resistance and gingivitis." (PMID 33849511, 2021). "Male rats with T2DM had an increase in the body weight, the increased levels of glucose, glycated hemoglobin (HbA1c), insulin, leptin, triglycerides and total cholesterol, and an increase in the insulin resistance index." (PMID 35008624, 2021). "The results of the tests showed that the level of glucose, insulin, and insulin resistance significantly increased in the PCOS rats compared to the healthy control group." (PMID 33842824, 2021). "Evaluation of insulin requirement is an alternative method for the determination of insulin resistance." (PMID 34577866, 2021). "While both insulin resistance and decreased insulin secretion were independent correlates of dysglycemia, we found a significantly higher predictive value for insulin resistance." (PMID 34206745, 2021). "LCFAs likely cause insulin resistance by promoting the accumulation of toxic lipid species such as ceramide and DAG in insulin-sensitive tissues and by increasing ROS production." (PMID 33923531, 2021). "Like psoriasis, T2DM is a complex disease with a multifactorial etiology, characterized by peripheral and hepatic insulin-resistance, as well as impaired insulin secretion from pancreatic beta cells." (PMID 33834030, 2021). "High fat diet (HFD) feeding is a widely used strategy to drive weight gain and insulin resistance, and has been used to study the effects of high caloric intake on autophagy in insulin-responsive tissues." (PMID 34336862, 2021). "In T2DM, insulin action and/or insulin secretion are impaired, and impaired insulin secretion is called insulin resistance." (PMID 35052549, 2021). "Promoting insulin secretion and ameliorating insulin resistance are the most important approaches in preventing DM and its complications." (PMID 34764939, 2021). "Two studies also evaluated fasting serum insulin levels and combined the two measures to compute the Homeostatic Model Assessment of Insulin Resistance (HOMA-IR) score, but only one yielded statistically significant improvement of 20.8% post-intervention." (PMID 34520483, 2021).
Insulin resistance (continued). "The serum insulin level was reduced, insulin resistance was reduced, and insulin sensitivity was enhanced." (PMID 34439921, 2021). "The same participants have reduced insulin secretion optimized for insulin resistance, despite increased BMI." (PMID 33490287, 2021). "In type 2 diabetes (T2DM), the insulin action and/or insulin secretion is impaired, latter is called insulin resistance." (PMID 34003397, 2021). "Other methods were used in this study to induce insulin resistance in 3T3L1 adipocytes such as treatment with high insulin, dexamethasone, and TNFα." (PMID 33498179, 2021). "In conclusion, combating insulin resistance by P. harmala is a novel machinery in attenuating the insidious progression of AD by enhancing both insulin and GLP-1 trajectories in the hippocampus favoring GLUT4 production." (PMID 34103557, 2021). "The synergistic effects of elevated cellular cortisol and insulin, for example, on lipoprotein lipase activity, result in insulin resistance and impaired glucose control with elevated circulating free fatty acids." (PMID 33270115, 2021). "Dietary fibers intake of patients with PCOS is negatively correlated with insulin resistance, fasting insulin (FINS), glucose tolerance, and androgen levels." (PMID 35185786, 2021). "Fasting serum insulin, Homeostatic Model Assessment for Insulin Resistance, and hemoglobin A1 were elevated in the Abnormal Group (P<0.05), showing the presence of insulin resistance in individuals with abnormal higher serum TSH levels." (PMID 33718264, 2021). "It is known that elevated insulin and insulin resistance are involved in the metabolic etiology of NAFLD." (PMID 35052736, 2021). "Since RVD1 can enhance Pdx gene expression, augment insulin secretion, reduce insulin resistance, and enhance insulin sensitivity, it is deduced that it (RVD1) is involved in the β cell regeneration process." (PMID 33546300, 2021). "If the insulin values are elevated, the diagnosis of insulin resistance, hyperinsulinemia, or even type 2 diabetes is made based on glucose." (PMID 35056318, 2021). "Insulin resistance is understood to be the inability of cells to use glucose, and the glucose-reducing effects of insulin are abnormal, leading to hyperglycemia, and T2DM." (PMID 33858419, 2021). "Nonetheless, olanzapine induced higher insulin resistance and consequently, increased insulin levels." (PMID 34335273, 2021). "This subset, characterized by elevated insulin levels, elevated triglyceride levels and insulin resistance are much harder to characterize than the MHO group and are predisposed to subsequent development of T2DM and coronary artery disease." (PMID 34943258, 2021). "In summary, maternal Ca restriction during pregnancy alters postnatal insulin secretion for three generations and also sex-specifically affects postnatal insulin resistance." (PMID 34209784, 2021). "LPIR is a non-insulin dependent fasting test that quantifies one of the earliest manifestations of insulin resistance—dyslipidemia characterized by elevations in triglyceride and lower high-density lipoprotein cholesterol concentrations." (PMID 34084151, 2021). "Adipocytes differentiated from young-donor ASCs also presented a decrease in insulin-induced phosphorylation of Akt, a key enzyme involved in short-term metabolic responses to insulin, in favor of a cellular insulin resistance at P7 and P11." (PMID 34544550, 2021). "To better understand clinical insulin resistance, we will first review how insulin uses signaling factors to control metabolic processes." (PMID 34766133, 2021). "Studies have shown that PPARα activation in obese and insulin-resistant animal models can effectively stimulate fatty acid oxidation and inhibit the lipid accumulation in liver and muscle tissues, improving insulin sensitivity and insulin resistance." (PMID 34443619, 2021).
Insulin resistance (continued). "Collectively, our results indicate that the phosphorylation of insulin signaling pathway proteins induced by PM2.5 instillation contributed to insulin resistance in the rat liver." (PMID 34745386, 2021). "The inflammatory cytokines, such as interleukin-1β (IL-1β) which is primarily driven by NF-κB and/or NLRP3 inflammasome activation, were related to islet inflammation and insulin secretion as well as the development of insulin resistance." (PMID 35111067, 2021). "The skeletal muscle represents about 40% of the body mass, being responsible for almost 80% of insulin-stimulated glucose uptake in healthy subjects, and is considered the major site of peripheral insulin resistance." (PMID 34440850, 2021). "Strikingly, we found that the blood glucose, insulin, homeostatic model assessment for insulin resistance (HOMA-IR), as well as triglyceride were elevated upon SARS-CoV-2 infection in comparison to healthy control, whereas the HDL-C was significantly reduced." (PMID 34916489, 2021). "A comparable β cell mass and a trend toward increase in insulin levels between the female mTOR-KOPlacenta and controls suggested insufficient compensation to combat insulin resistance present in the mTOR-KOPlacenta offspring." (PMID 34032632, 2021). "Serum IGF-I and total IGFBP-3 levels, fasting plasma glucose levels, lipid profiles, insulin levels, C-peptide levels, homeostasis model assessment of insulin resistance (HOMA-IR) index, and glycated hemoglobin (HbA1c) levels were measured." (PMID 34239560, 2021). "Intracellular serine/threonine kinases are activated by inflammation factors and catalyze the inhibitory phosphorylation of key proteins of the insulin signaling pathway, leading to insulin resistance." (PMID 34299261, 2021). "From a clinical point of view, it is interesting to note the reduction of insulin levels and insulin resistance, which are reflected in the reduction of the HOMA index." (PMID 34444671, 2021). "Our results showed a significant increase in levels of fasting blood glucose and insulin (4 and sevenfold increase, respectively) in addition to an increase in insulin resistance index in untreated diabetic obese rats." (PMID 34667196, 2021). "Not only the different kinds of carbohydrates affect blood glucose levels or insulin secretion differently, but also the quantity ingested and body fat influence the development of insulin resistance." (PMID 33661377, 2021). "Intuitively, T2DM is induced either by insulin resistance (IR) from insulin-responsive cells and tissues or pancreatic β‐cell dysfunction, leading to inadequate secretion of insulin." (PMID 35087408, 2021). "The imbalance between insulin secretion and insulin sensitivity results in hepatic insulin resistance which is well known in T2D." (PMID 36994321, 2021). "Pregnant animals usually develop a transient insulin resistance which is compensated by increases in glucose-stimulated insulin secretion." (PMID 33440789, 2021). "Insulin resistance can be evaluated non-invasively by insulin sensitivity indices (ISI) such as the Mcauley index (MCAi), which is a function of the fasting insulin and triglycerides." (PMID 33957929, 2021). "Two main characteristics of T2DM are the pancreatic β-cell dysfunction and insulin resistance in various insulin target tissues such as the liver, skeletal muscle and adipose tissues." (PMID 34360682, 2021). "Adipose tissue macrophages (ATMs) contribute to the development of insulin resistance by the release of several pro-inflammatory mediators, which can block insulin action in adipocytes and other tissues." (PMID 34440850, 2021). "Several studies have also reported an improved glucose homeostasis, potentially by direct effects on insulin resistance and insulin secretion." (PMID 34069853, 2021).
Insulin resistance (continued). "Our results found that insulin resistance and a compensatory increase in insulin secretion exist in KS patients, and the increased islet β-cell secretion function was statistically significant compared with those patients with hyperglycemia but without KS." (PMID 34852815, 2021). "GC act on insulin signaling through the binding to their receptors as shown by studies revealing a strong correlation between GR mRNA levels in the muscle and insulin resistance in diabetic patients." (PMID 33435513, 2021). "In the pancreatic islet α cells of T2DM patients, the insulin signaling pathways, such as Akt, are blocked, which leads to insulin resistance." (PMID 34751249, 2021). "This is believed to be the main mechanism of the development of insulin resistance and altered insulin secretion." (PMID 34239695, 2021). "It additionally suppresses the diet-induced adipose inflammation, insulin resistance, and hepatic steatosis and decreases circulating levels of triglycerides and cholesterol while elevating insulin secretion." (PMID 34645915, 2021). "Collectively, the results obtained in in vitro and animal models indicate that dietary flavonoids can modulate the insulin signaling in peripheral tissues and, thus, alleviate the insulin resistance in T2D." (PMID 34208379, 2021). "Under insulin resistance/hyperinsulinemia, ET-1 can suppress insulin-induced Akt activation in VSMCs to exacerbate the development of hypertension and atherosclerosis." (PMID 33937238, 2021). "For the assessment of insulin resistance, the homeostatic model assessment of insulin resistance was used as fasting glucose (in mmol/L) × fasting insulin (in μ/L)/22.5." (PMID 33878166, 2021). "Glucagon, cortisol, and epinephrine are mainly responsible for hepatic insulin resistance, while peripheral insulin resistance is attributed to the derangement of the insulin-signaling pathway in muscles and adipose tissue." (PMID 33981655, 2021). "Despite some debate, the majority of data on insulin sensitivity show that TMAO drives muscle carbohydrate and lipid metabolism associated with insulin resistance and heart failure." (PMID 34445033, 2021). "Insulin resistance is classically defined as the body's impaired ability to respond to the actions of the hormone insulin on glucose homeostasis." (PMID 34778146, 2021). "Insulin resistance significantly increases insulin secretion, which in turn influences bone metabolism via insulin-like growth factor 1 (IGF-1)." (PMID 34769010, 2021). "Effective periodontal therapy reduced insulin resistance and improved periodontal health status and insulin sensitivity in patients with T2DM and chronic periodontitis." (PMID 34539410, 2021). "Nevertheless, another study shows that GPR40 contributes to the maintenance of basal metabolism, and GPR40−/− mice had increased body weight, higher insulin levels, insulin resistance, cholesterol, FFA on an LFD." (PMID 34943862, 2021). "In our study, the result showed that MFAE can reduce insulin concentration, increase insulin sensitivity, and improve insulin resistance symptoms in rats." (PMID 34724560, 2021). "With this in mind, it is notable that iPLA2ζ null mice were protected from diet‐induced obesity and insulin resistance due to the upregulation of insulin signaling, and more work should be done to assess the translatability of this finding." (PMID 33433056, 2021). "Women with an early diagnosis of GDM (early GDM) had higher fasting glucose, fasting insulin, higher insulin resistance and lower insulin sensitivity at baseline compared with women with a later diagnosis of GDM (late GDM)." (PMID 33467738, 2021). "There is a struggle to lower blood glucose, decrease insulin levels and prohibit insulin resistance." (PMID 34299610, 2021). "Insulin resistance occurs as a result of the decreased response to the effects of insulin in peripheral tissues (i.e. liver, adipose tissueand muscle) and is related to hyperinsulinemia." (PMID 34092237, 2021).
Insulin resistance (continued). "All these genes appear in adipocytokine signaling as well as insulin signaling or insulin resistance." (PMID 34564389, 2021). "Type 2 diabetes mellitus (T2DM) is a metabolic disease triggered by insulin resistance or impaired insulin secretion and characterized by hyperglycaemia." (PMID 34675276, 2021). "One connection between obesity-induced inflammation and hormonal control of lipolysis is insulin resistance, which manifests as impaired insulin-mediated suppression of lipolysis." (PMID 33610548, 2021). "Studies that evaluated the effect of RV on glucose, insulin, HbA1c, and insulin resistance (HOMA-IR) levels were included." (PMID 33430470, 2021). "Being aware that Zn stabilizes insulin hexamers and participates in its storage in the pancreas, we suspected that in women with insulin resistance there would be much less of it." (PMID 34203167, 2021). "In a hyperinsulinaemic-euglycemic clamp study in subjects with hypertriglyceridaemia and insulin resistance, pemafibrate treatment improved hepatic glucose uptake and insulin sensitivity." (PMID 33392801, 2021). "Insulin resistance occurs when a higher dose of insulin is required to produce the same effects on glucose storage." (PMID 33435513, 2021). "At the cellular level, insulin resistance is described as poor insulin signaling strength from insulin receptor downstream to the end substrate of the cascade." (PMID 33953863, 2021). "Obesity induces insulin resistance affecting peripheral tissues, which results in a compensatory increase of pancreatic insulin secretion." (PMID 34015524, 2021). "Children and adolescents with obesity exhibited normoglycemia, but showed insulin resistance as evidenced by the increased insulin concentrations (p = 0.006) and HOMA values (p = 0.004)." (PMID 33917063, 2021). "The AD brain exhibits insulin resistance, and T2DM is a major risk factor for AD; therefore, insulin secretagogues which can induce MUTYH degradation are promising therapeutic agents for the prevention of the AD pathogenesis." (PMID 34970419, 2021). "Several mechanisms can induce insulin resistance by interfering with the insulin signaling cascade, i.e., elevated blood glucose, endoplasmic reticulum stress, cellular inflammation, and inherited variations in the signaling molecules." (PMID 34388207, 2021). "Similar to what occurs in healthy cells during diabetes and insulin resistance, EC cells develop abnormalities in the insulin and insulin-like growth factor-1 (IGF-1) signalling pathways, both of which are involved in cancer cell growth." (PMID 33946913, 2021). "On the one hand, CKD reduces insulin sensitivity (and increases insulin resistance) and leads to β-cell dysfunction and insulin secretion defects in the late stage." (PMID 35174179, 2021). "Multiple studies revealed that women with GDM had varying insulin resistance levels and reduced insulin sensitivity after delivery." (PMID 34229731, 2021). "We found that a fructose-rich diet elicited an increase in insulin resistance index in the liver and decreased activation of insulin downstream effector kinase Akt." (PMID 33921866, 2021). "Vitamin D has been proven to be beneficial for various steps in the progression and worsening of severity of NAFLD, including improvements in insulin secretion and insulin resistance, adipose tissue inflammation, hepatic inflammation, and hepatic fibrosis." (PMID 34604270, 2021). "The HOMA-IR scores of the CTRL and model groups were 1.3 ± 0.1 and 6.3 ± 0.5, respectively, which showed that the CTRL had optimal insulin sensitivity; however, the model group exhibited significant insulin resistance because of HFD feeding." (PMID 33510408, 2021). "This prepubertal insulin resistance sets the stage for further disruption in glucose and insulin regulation after puberty, as was observed in mice from studies discussed earlier." (PMID 33467592, 2021).